GATA3 (GATA binding protein 3)
Diseases named in the same sentence as GATA3 in open-access papers (continued):
Sharing a sentence is not in itself a finding about the gene and the disease.
breast carcinoma (continued). "We found expression of GATA-3 in an exclusive nuclear location of epithelial cells of canine mammary tumors." (PMID 37483298, 2023). "To directly test if deficiency of Gata3 in luminal tumor cells regulates c-Fos and Fra1 expression in mammary tumor development, we take advantage of the MMTV-PyMT luminal type mammary tumor model system we established." (PMID 37353480, 2023). "The DMBA carcinogenesis group showed enhanced immunostaining for GATA-3 immunohistochemistry, a sign of increased mammary cancer metastasis." (PMID 38125593, 2023). "The performance analysis showed that the expression of GATA-3 in ≥79.4% of cells effectively predicted survival or death in dogs with mammary tumors." (PMID 37483298, 2023). "Here, we evaluated the frequency of GATA-3 expression in mammary tumors of dogs and its relationship with prognostic factors and survival." (PMID 37483298, 2023). "Nevertheless, there are few studies related to the expression of GATA-3 in mammary neoplasms of female dogs." (PMID 37483298, 2023). "IS6 was mainly distinguished by an enrichment of mutations in GATA3, which disrupts epithelial-to-mesenchymal transition (EMT) and inhibits the tumor-initiating ability of luminal progenitor cells and metastasis in breast cancer." (PMID 35154121, 2022). "We predict transcription factors known to be involved in cancer as well as novel candidates to drive hypo-methylated regions such as FOXA1 and GATA3 in breast cancer, FOXA1 and TWIST1 in prostate cancer and NFE2L2 in lung cancer." (PMID 35331302, 2022). "These regions are located hundreds kbp from the capture region and co-localize with DNAse I hypersensitive sites, CTCF, FOXA1, GATA3, and ERα binding sites in breast cancer and normal breast epithelial cell lines." (PMID 35176995, 2022). "We knocked down GATA3 in the human luminal breast cancer cell line, T47D, and again found that the expression of genes associated with luminal differentiation, such as CDH1 and ESR1, was significantly downregulated." (PMID 34976209, 2022). "It remains elusive if GATA3 can be a therapeutic target or if these GATA3 mutant breast cancer cells are sensitive to specific chemicals." (PMID 35154280, 2022). "GATA3 can promote breast cancer invasion and metastasis through epithelial-mesenchymal transition (EMT)." (PMID 35993027, 2022). "For example, TF GATA3 is a definitive cell marker of breast cancer (Figure 1A4); and (v) TF Pmarker: TFs, which play roles as potential markers." (PMID 34986601, 2022). "Breast carcinoma can be identified by positivity to GATA-3 and sometimes hormone receptors, whereas colorectal carcinoma is often positive to SATB2." (PMID 35328664, 2022). "Consistently, we found that GATA3 was also negatively related to the immunological characters of breast cancer." (PMID 35647011, 2022). "We validated two TFs, FOXA1 and GATA3 in breast cancer cells, and found that their binding indeed mediates focal hypo-methylation." (PMID 35331302, 2022). "Our results present MDM2 as a therapeutic target in the substantial cohort of ER-positive, GATA3-mutant breast cancer patients." (PMID 35440675, 2022). "In the context of metastasis, GATA3 overexpression in LM2-4175 breast cancer cell line, an aggressive derivative of MDA-MB-231, inhibits cancer cell expansion in the lung." (PMID 35846378, 2022). "We next set out to validate experimentally if the TFs FOXA1 and GATA3 drive changes in DNA methylation in common breast cancer cell lines." (PMID 35331302, 2022). "The p38γ MAPK pathway has been suggested to mediate EMT of breast cancer through the p38γ MAPK/GATA3/miR-200b/Suz12." (PMID 35179516, 2022). "We further confirmed that GATA3 and basal marker expression levels are inversely correlated in human basal-like breast cancers." (PMID 34976209, 2022).
breast carcinoma (continued). "In this study, we have established three luminal breast cancer cell lines that stably express different GATA3 truncation mutants found in breast cancer." (PMID 35154280, 2022). "In accordance with the oncosuppressor role of GATA3 and our previously generated data, PDOs derived from the GATA3-mutant primary breast cancer significantly proliferated more compared to GATA3 wild-type PDOs." (PMID 35440675, 2022). "Pan-cancer analyses screened that GATA3 was negatively correlated with the immune status of several cancers, such as breast cancer and BLCA." (PMID 35647011, 2022). "It has been previously reported that GATA3 expression is low in TNBC and its deficiency or alterations lead to breast cancer aggressiveness." (PMID 35804829, 2022). "MGP, TRPS1, and GATA3 were positive in 1075/1201 (89.5%), 1109/1201 (92.3%), and 922/1201 (76.8%) breast carcinomas, respectively." (PMID 36284362, 2022). "Furthermore, our findings suggest that GATA3 mutations may drive resistance to hormonal therapy by upregulating the PI3K/Akt/mTOR pathway, suggesting that inhibition of MDM2 may help overcome the resistance to PI3K/Akt/mTOR inhibition and/or to endocrine therapy in GATA3-deficient breast cancer." (PMID 35440675, 2022). "We show that inhibition of MDM2 is synthetically lethal in GATA3-mutant and GATA3-depleted breast cancer cells." (PMID 35440675, 2022). "In breast cancer, FOXA1 and GATA3 are functionally linked with estrogen receptor alpha (ERα), and high level of expression of all three strongly correlates with the luminal subtype of breast tumors also referred as ER positive tumors (ER +)." (PMID 35331302, 2022). "This shows that overexpressed GATA3 can indeed mediate DNA hypo-methylation in normal cells at sites bound in breast cancer cells." (PMID 35331302, 2022). "In our case, a metastasis from the patient’s known breast cancer was excluded using immunohistochemical markers for GATA-3, mammaglobin, and BRST2." (PMID 34312795, 2022). "Neuroblastoma and breast cancer cell lines, for which a GATA-3 dependency has been established, were identified." (PMID 36329027, 2022). "The Luminal B2 subtype of HER2-positive breast cancer, which overexpressed GATA3, BCL2, and ESR1 genes, was found to account for roughly half of all HER2-positive breast cancer subtypes." (PMID 36034650, 2022). "In MCF7 human breast cancer cells, GATA3, through its transcription regulation of CCND1 and in association with PARP1 promotes cell proliferation and tumorigenesis by facilitating the G1 to S phase transition in the cell cycle." (PMID 35846378, 2022). "We next compared MGP, TRPS1, and GATA3 expression in 1201 breast carcinoma cases of different subtypes, including 140 metaplastic breast carcinoma cases, using immunochemistry staining." (PMID 36284362, 2022). "We compared MGP, TRPS1, and GATA3 expression in different subtypes of breast carcinoma of (n = 1201) using IHC." (PMID 36284362, 2022). "We confirmed that expression of GATA3 and basal markers are inversely correlated in human basal-like breast cancers." (PMID 34976209, 2022). "GATA3 is a reliable biomarker for breast carcinomas and is frequently used to determine the tissue of origin to confirm a diagnosis." (PMID 35154280, 2022). "Meanwhile, another study from our group showed that Notch3 can inhibit EMT in breast cancer epithelial cells by transactivating GATA3 and Kibra." (PMID 36139447, 2022). "Recently, it was reported that GATA binding protein 3 (GATA3), a transcription factor, elevated the miR-29b level in breast cancer whereas the destruction of miR-29b enhanced metastasis and accelerated EMT." (PMID 36140219, 2022). "Recent evidence suggests that GATA3 as a strong and independent predictor of clinical outcome in human luminal breast cancer." (PMID 35488350, 2022).
breast carcinoma (continued). "A number of studies have demonstrated that GATA3 is a superior marker for ER+ breast carcinoma than GCDFP-15 or mammaglobin, with a sensitivity consistently over 90%." (PMID 36284362, 2022). "We interrogated the candidates for well-developed drug targets and identified MDM2 as the top druggable gene whose knock-down significantly reduced cell viability in the two GATA3-mutant breast cancer cell lines (MCF-7 and KPL-1)." (PMID 35440675, 2022). "On the other hand, 82% (n = 17) of p18mt;Gata3+/- mammary tumors were highly heterogeneous, poorly-differentiated, ER negative, Ck5, Ck14 or SMA positive basal-like tumors." (PMID 34976209, 2022). "By investigating MMTV-PyMT mouse mammary tumors, we found that expression of Gata3 negatively correlates with basal differentiation markers in tumor cells." (PMID 34976209, 2022). "Pathological and IHC analysis revealed that, like primary p18mt;Gata3+/- mammary tumors, regenerated p18mt;Gata3+/- mammary tumors were poorly differentiated, positive for Ck5 and Ck14, and negative for ERα." (PMID 34976209, 2022). "To build a murine model system for investigating the role of Gata3 in controlling basal differentiation in luminal tumor cells, we screened 19 spontaneous mammary tumors developed in PyMT mice by western blot and IHC." (PMID 34976209, 2022). "The mammary tumor-free survival was reduced from a mean age of 21 months in p18mt mice to 18 months in p18mt;Gata3+/- mice." (PMID 34976209, 2022). "In the same time period, all mice that received 5 x 105p18mt;Gata3+/- tumor cell transplants, 1/10 the number of cells in comparison with p18mt transplants, developed large mammary tumors (2,275 ± 312 mm3)." (PMID 34976209, 2022). "In sum, we successfully developed a murine luminal type mammary tumor system in which mammary tumor cells express high levels of Gata3 and are capable of generating Gata3 positive luminal tumors once transplanted into the MFPs of mice." (PMID 34976209, 2022). "Expression of Gata3 negatively correlated with basal differentiation markers in MMTV-PyMT mammary tumor cells." (PMID 34976209, 2022). "Starting from as early as 8 months, p18mt;Gata3+/- mice (n = 34) developed mammary tumors whereas p18mt mice (n = 27) developed mammary tumors after 12.5 months." (PMID 34976209, 2022). "GATA3 promotes differentiation of luminal cells and inhibits infiltration and metastasis of breast cancer cells." (PMID 33795819, 2021). "In basal-like breast cancer, p65 and GATA3 were shown to promote and inhibit FOXC1 expression, respectively." (PMID 33854062, 2021). "Together, these clinical findings are consistent with the results from our mice cohorts; thereby suggesting an opportunity to use murine systems to further explore how BRCA1 interacts with GATA3 to control EMT in breast cancers." (PMID 34373738, 2021). "To further verify that these genes were regulated by these three TFs, we analyzed gene-expression data from knockdown (FOXA1 and ESR1) and over-expression (GATA3) experiments in breast cancer cell lines (see “Methods” section)." (PMID 34518541, 2021). "have assessed GATA3 expression in a set of invasive ductal carcinomas samples as well as matched metastatic breast carcinomas using the tissue microarray method." (PMID 34094972, 2021). "This behavior was present in both METABRIC(LumA) and TCGA-BRCA(LumA), thus revealing the presence of two independent expression programs within GATA3 that are consistent across different breast cancer cohorts." (PMID 33957863, 2021). "Recognition of melanoma is important to avoid misdiagnosis of carcinoma, especially with the history of breast cancer and the expression of GATA3 by tumor cells, which is usually used as a marker for mammary carcinoma." (PMID 34449584, 2021). "Expression of GATA3 was significantly higher in breast cancer tissues compared with ANCTs (Ratio of mean expressions (RME) = 4.99, P value = 3.12E−04)." (PMID 34094972, 2021).
breast carcinoma (continued). "Previous studies have demonstrated that GATA3 and GCDFP15 expression were positively associated with breast carcinoma and breast cancer metastasis." (PMID 33776925, 2021). "Prompted by the finding that Gata3 functions downstream of Brca1 in suppressing EMT in breast cancers, we then examined if ectopic Gata3 in Brca1-deficinet tumor cells suppresses their potential for tumor initiation and metastasis." (PMID 34373738, 2021). "The most recent breast cancer GWAS identified a 2–5 fold increased enrichment of risk SNVs in REs, mostly mapping to the binding sites for breast cancer–associated transcription factors including FOXA1, ESR1, GATA3, E2F1, and TCF7L2." (PMID 34439109, 2021). "KIAA1429 enhanced liver tumorigenesis through regulating GATA3 in a m6A-dependent manner and also act as an oncogene in breast cancer by modulating CDK1." (PMID 33748145, 2021). "Expression analysis of the mentioned genes in a cohort of breast cancer patients revealed overexpression of GATA3 in breast cancer tissues compared with ANCTs." (PMID 34094972, 2021). "ZNF-337-AS1/miR-485/FOXA1 and ZNF-337-AS1/miR-485/GATA3 are other putative functional axes in the pathogenesis of breast cancer." (PMID 34094972, 2021). "GATA3-positive breast cancers have been shown to be highly differentiated, with resulting tumours two-fold larger in size than control tumours." (PMID 34099719, 2021). "In the normal mammary gland, GATA3 is required for luminal epithelial cell differentiation, and its expression is progressively lost during luminal breast cancer progression as cancer cells acquire an immature phenotype." (PMID 33803938, 2021). "Our finding identifies GATA3 as the first transcription factor that functions downstream of BRCA1 to suppress EMT in breast cancers." (PMID 34373738, 2021). "According to the literature, all 3 identified LNM-upregulated genes, i.e. ATG10, GATA3 and S100B, are considered markers of breast cancer cells and their invasive potential." (PMID 33658651, 2021). "Only GATA3 represented different expression profiles including the high expression for breast cancer and low expression for ovarian cancer." (PMID 33907495, 2021). "Hi-C has been used to investigate the role of RUNX1, ER, and GATA3 on chromosome conformation in tumorigenesis and development of breast cancer." (PMID 34439109, 2021). "For instance, loss of GATA3 promotes the proliferation, migration, invasion, and EMT of bladder cancer, gastric cancer, breast cancer, and osteosarcoma." (PMID 34399777, 2021). "GATA3 expression was shown to be required for the high mobility group box-containing factor TCF7L2 to bind to about 50% of TCF7L2 sites in the ER-positive breast cancer cell line MCF-7, and these sites were enriched in GATA3 but not TCF7L2 motifs." (PMID 34831189, 2021). "The expression of GATA3 was significantly higher in breast cancer tissues compared with ANCTs (Ratio of mean expressions (RME) = 4.99, P value = 3.12E−04)." (PMID 34094972, 2021). "In contrast, the top predictive variants of low metastatic risk in breast cancer are DAXX, MCL, and GATA3 amplification." (PMID 34795255, 2021). "FOXA1 and GATA3 have critical roles in ER + breast cancer in that these transcription factors form a regulatory network with ERα." (PMID 34238359, 2021). "FOXA1, GATA3 and SPDEF are key drivers of estrogen receptor-positive (ER+) breast cancer risk as well as cancer progression." (PMID 34712617, 2021).
breast carcinoma (continued). "The CpG sites affected are at enhancer regions with TFBS for ER-alpha, FOXA1, and GATA3, all known to be important for the luminal breast cancer phenotype." (PMID 33926515, 2021). "Promotes M2 polarization of macrophages and NSCLC cell progression via directly inhibiting miR-4319.GNAS-AS1/miR-433-3p/GATA3 axis promotes the proliferation and metastasis of ER+ breast cancer cells by accelerating M2 macrophage polarization." (PMID 34295338, 2021). "GATA3 is another target genes of miR-132-3p based on miRTArbase and miRWalk databases, therefore APTR/miR132-3p/GATA3 is another possible route of participation of APTR in breast cancer." (PMID 34094972, 2021). "By targeting the Zpo2 to GATA3 promoters, ZBTB32 promotes the deregulation of GATA3 target genes, leading to the progression of aggressive breast cancer." (PMID 35095893, 2021). "Several known proteins were also selected including ERalpha, which is overexpressed in early stages of breast cancer and GATA3 which plays an integral role in breast luminal cell differentiation and breast cancer progression." (PMID 34744522, 2021). "Our findings suggest a critical role of Gata3 loss in driving CSC function and metastasis, and support the development of therapeutic drugs enhancing GATA3 function or targeting its downstream pathway to treat metastatic breast cancers." (PMID 34373738, 2021). "Surprisingly, in the same time period all mice (4 out of 4) that received 1 x 106p18mt;Gata3+/- tumor cell transplants developed huge mammary tumors (1440 ± 350 mm3 in size) and exhibited clinical sign of dyspnea." (PMID 34373738, 2021). "Pathological analysis revealed that, like primary p18mt;Gata3+/- mammary tumors, regenerated p18mt;Gata3+/- mammary tumors were poorly differentiated, highly aggressive, invaded into the surrounding muscles, and metastasized to the lungs." (PMID 34373738, 2021). "In this paper, we found that BRCA1 and GATA3 expressions are positively correlated and that BRCA1 mutation is associated with the enhanced methylation of the GATA3 promoter and reduced expression of the GATA3 gene in human breast cancers." (PMID 34373738, 2021). "Our finding demonstrates that GATA3 functions downstream of BRCA1 to suppress EMT in controlling mammary tumor initiation and metastasis." (PMID 34373738, 2021). "We discovered that GATA3 functions downstream of BRCA1 to suppress EMT in controlling mammary tumor initiation and metastasis." (PMID 34373738, 2021). "77% (13 out of 17) of p18mt;Gata3+/- mammary tumors were positive for EMT markers including fibronectin (Fn), vimentin (Vim), CD29, and EMT-TFs in 2-60% of the tumor cells." (PMID 34373738, 2021). "Our finding, for the first time, demonstrates that GATA3 functions downstream of BRCA1 to suppress EMT in controlling mammary tumor initiation and metastasis." (PMID 34373738, 2021). "p18mt;Gata3+/- mammary tumors displayed typical pathological characteristics of poorly-differentiated tumors--highly heterogeneous cell types with increased necrosis, squamous metaplasia, spindle cells, nuclear-cytoplasm ratio, and mitotic indices." (PMID 34373738, 2021). "We examined EMT markers including Vim, Fn, E-cad, and EMT-TFs and found that all EMT markers positively stained in p18mt;Brca1+/- primary mammary tumors and its related metastasis were also detected in p18mt;Gata3+/-counterparts." (PMID 34373738, 2021). "A wide set of diagnostic tests is performed and finally cytologic findings after repeated CSF confirm leptomeningeal infiltration by breast carcinoma (panCK+, GATA3+)." (PMID 31895768, 2020).